RPS26P47 (ribosomal protein S26 pseudogene 47)
Gene: Processed pseudogene on chromosome 13 (100,539,901 to 100,540,248, reverse strand). Ensembl gene ENSG00000234354.
Diseases named in the same sentence as RPS26P47 in open-access papers:
RPS26P47 is named in the same sentence as 2 diseases in open-access papers, as found by Europe PMC text mining. Sharing a sentence is not in itself a finding about the gene and the disease. The quoted sentences say what the papers report.
ovarian carcinoma (1 paper, 2019). A malignant neoplasm originating from the surface ovarian epithelium. "All these findings indicated that RPS26P15, AC004057.1, RPS26P31, RPS26P6, RPS26P3 and RPS26P47 were the most potential pseudogenes in regulating hsa-miR-363-3p in ovarian cancer." (PMID 31794425, 2019). "Among 56 predicted pseudogenes, only 6 pseudogenes (RPS26P15, AC004057.1, RPS26P31, RPS26P6, RPS26P3 and RPS26P47) were significantly upregulated in cancer samples (compared to normal samples) and advanced stage of ovarian cancer (compared to early stage ovarian cancer)." (PMID 31794425, 2019).
cancer (1 paper, 2019). A tumor composed of atypical neoplastic, often pleomorphic cells that invade other tissues. "Finally, only 6 pseudogenes, RPS26P15, AC004057.1, RPS26P31, RPS26P6, RPS26P3 and RPS26P47 were significantly upregulated in cancer tissues when compared with normal controls." (PMID 31794425, 2019).